AFP (alpha fetoprotein)
Diseases named in the same sentence as AFP in open-access papers (continued):
Sharing a sentence is not in itself a finding about the gene and the disease.
steatosis (16 papers, 2005 to 2025). Increased lipid within the cytoplasm of cells. "As steatosis was the only pathological change in the remnant liver, this may have caused the persistently elevated AFP level in this patient." (PMID 22559879, 2012). "In this study, steatosis was also associated with the presence of necroinflammation and fibrosis, and thus, it is not clear whether it is the extent of liver injury or steatosis per se that leads to the elevation in AFP." (PMID 23209913, 2012). "We found a significant correlation of steatosis with SteatoTest, alpha-fetoprotein (AFP), HbA1c, and triglycerides." (PMID 36941982, 2023). "Higher rates were reported in patients with elevated AFP: two thirds (66.6%) had severe necroinflammatory activity, severe non-alcoholic steatohepatitis was observed in 67.8%, and severe steatosis in 80.1%." (PMID 32341704, 2020). "We also considered it possible that hepatocyte steatosis and subsequent hepatic regeneration are responsible for the elevation of serum AFP levels in patients with MS." (PMID 27121855, 2016). "In our patient, steatosis was the only abnormality of the hepatic parenchyma detected on pathological examination, and was the only condition that could have caused the persistently elevated AFP level, as laboratory tests and imaging results eliminated all other possible causes." (PMID 22559879, 2012). "In our study a negative correlation was found between lower serum albumin and AFP among patients with steatosis." (PMID 22675639, 2012). "We were also able to show a significant correlation of AFP with steatosis (CAP)." (PMID 36941982, 2023). "Interaction between AFP expression and steatosis warrants further study." (PMID 35862314, 2022). "In patients with steatosis, AFP production may be stimulated by cytokines, or may result from altered interactions between hepatocytes." (PMID 22559879, 2012). "So in the absence of traditional causes of elevated serum AFP, steatosis should be among the differential diagnoses of elevated serum AFP levels in patients with chronic HCV infection." (PMID 22675639, 2012). "Furthermore, levels of many of these biomarkers including AFP are elevated in the setting of steatosis and liver regeneration which can lead to a false positive diagnosis for HCC or not elevated in the setting of smaller tumors leading to a false negative diagnosis." (PMID 29944670, 2018). "Higher levels of serum AFP may correspond to the presence of steatosis among chronic HCV." (PMID 22675639, 2012). "There was a significant correlation of steatosis (CAP values) with ALT (r = 0.77, p < 0.0001), AST (r = 0.39, p < 0.05), GGT (r = 0.83, p < 0.0001), AFP (r = 0.42, p < 0.05), HbA1c (r = 0.59, p < 0.01), and triglycerides (r = 0.74, p < 0.00001)." (PMID 36941982, 2023). "Our diagnosis of FLD was more defined since the grading of steatosis and NASH was based on Fibromax parameters, allowing a more precise correlation between AFP serum levels and FLD severity." (PMID 32341704, 2020). "Increased serum AFP correlated with advanced age, severe necroinflammatory activity detected by FibroMax, severe NASH, severe steatosis, low platelets, increased values of AST, and ALT." (PMID 32341704, 2020). "FibroMax estimations revealed significant differences: in patients with normal AFP levels, severe necro-inflammatory activity was noted in 55.2% of the cases, severe NASH in 41%, and severe steatosis in 62.4%." (PMID 32341704, 2020). "In chronic HCV with steatosis, elevated AFP levels correlated positively with HAI and negative significant correlation with albumin level." (PMID 22675639, 2012). "In conclusion, this study has demonstrated that patients with chronic HCV and steatosis have higher AFP levels than those without steatosis." (PMID 22675639, 2012).
steatosis (continued). "Although both groups (with or without steatosis) are similar regarding underlying etiology (HCV) and were adjusting for risk factors of high levels of AFP and steatosis, AFP was highly significant among patients with chronic HCV and steatosis than patients without steatosis." (PMID 22675639, 2012). "AFP was significantly increased in CHC with steatosis than patients without steatosis (P < 0.001)." (PMID 22675639, 2012). "The present paper assessed clinical significance of elevated AFP in patients with CHC with and without steatosis." (PMID 22675639, 2012). "In this study we tried to determine the level of AFP among patients with chronic HCV, and evaluate its relation to the presence of steatosis among 100 patients with chronic HCV (50 with steatosis and 50 without steatosis) enrolled in our study." (PMID 22675639, 2012).
gastric tumor (15 papers, 2008 to 2025). "Gastric tumors predominantly arise in the gastric antrum and are frequently accompanied by distant liver metastases and elevated serum AFP levels." (PMID 40999892, 2025). "In particular, AFP expression is reportedly detectable in nearly half of gastric tumors with ENT differentiation." (PMID 37027114, 2023). "The stomach and liver originate from the primitive foregut during embryogenesis, suggesting that some gastric tumors may acquire hepatocellular features, culminating in AFP production." (PMID 40485723, 2025). "In this study, we discovered that AFP enhances the stability of oncoproteins c-MYC and c-MET, thereby facilitating the progression of liver and gastric tumors." (PMID 39135041, 2024). "The positive rate of AFP, CEA and CA19-9 with combined detection in the cardia cancer was higher than that in the other parts." (PMID 23672279, 2013). "The neuroendocrine component of composite gastric tumor demonstrated positive reactions for CGA and SP, while no reaction was observed for AFP." (PMID 22482081, 2012).
lymphoma (15 papers, 2015 to 2025). A malignant (clonal) proliferation of B- lymphocytes or T- lymphocytes which involves the lymph nodes, bone marrow and/or extranodal sites. "The tumor products AFP and microRNAs have been evaluated as potential diagnostic and prognostic biomarkers for lymphoma." (PMID 27747218, 2016). "Here, seven common plasma protein tumor markers (AFP, CA125, CA15-3, CA19-9, CA72-4, CEA, and CYFRA21-1) were selected to estimate the expression in each lymphoma patient and healthy individual." (PMID 38313801, 2024). "When 63 dogs with lymphoma were compared to 80 normal controls, high-stage lymphoma dogs (27 stage III, 15 stage IV, and 9 stage V) and male dogs had the highest average AFP serum levels." (PMID 27747218, 2016). "The absence of GFAP, CK18, CD30, cytokeratin and alpha-fetoprotein (AFP) expression ruled out differential diagnoses such as gliomas and lymphomas." (PMID 40556791, 2025). "SeekInCare for lymphoma detection utilized common cancer hallmarks, not specific characteristics of lymphoma (such as AFP for HCC)." (PMID 38313801, 2024). "Since then, specific binding of AFP to the AFPR has been demonstrated in a variety of human cancers or cancer cell lines, consistent with the high AFPR expression observed on tumor cell lines including colorectal, ovarian, breast, lung and lymphoma in our own studies." (PMID 37016369, 2023).
squamous cell carcinoma (15 papers, 2011 to 2025). A carcinoma arising from squamous epithelial cells. "Tumor markers, including squamous cell carcinoma (SCC) antigen, carbohydrate antigens 153 (CA153) and 125 (CA125), carcinoembryonic antigen (CEA), and alpha-fetoprotein (AFP), were all within normal ranges." (PMID 40432921, 2025). "The tumor markers such as squamous cell carcinoma (SCC) antigen, CA 125, CA19-9, CEA, and AFP may be elevated when the malignancy exists." (PMID 37047114, 2023). "Levels of tumor markers alpha-fetoprotein (AFP), carcinoembryonic antigen (CEA), carbohydrate antigen 19-9 (CA19-9), squamous cell carcinoma (SCC) antigen, pro-gastrin-releasing peptide (Pro-GRP), and prostate-specific antigen (PSA) were within the normal range." (PMID 33896422, 2021). "Serum levels of tumor markers were negative for carcinoembryonic antigen (CEA), CA125, CA19–9, squamous cell carcinoma (SCC), human chorionic gonadotropin (HCG) and alpha fetoprotein (AFP)." (PMID 26437718, 2015).
intrahepatic cholangiocarcinoma (14 papers, 2014 to 2026). A carcinoma that arises from the intrahepatic bile duct epithelium in any site of the intrahepatic biliary tree. "Laboratory tests are also useful in establishing the diagnosis, because alpha-feto protein (AFP) levels are usually normal or only slightly elevated in intrahepatic cholangiocarcinoma compared with HCC." (PMID 25608662, 2014). "The mechanisms underlying the acquisition of AFP production in neuroendocrine neoplasms remain unclear; however, the identification of genetic abnormalities commonly associated with intrahepatic cholangiocarcinoma suggests a potential derivation from AFP-producing intrahepatic cholangiocarcinoma." (PMID 39522069, 2025). "For example, one study developed an intrahepatic cholangiocarcinoma (ICC) scoring system (ie, −2.474−2.554×elevated Alpha-fetoprotein+2.537×elevated CA 19-9+2.451×obscure lesion boundary+3.164×Rim-like hyperenhancement+1.976×wash-out onset within 45s+2.976×marked wash-out within 3 min)." (PMID 39304213, 2025).
Oculomotor apraxia (14 papers, 2008 to 2025). Ocular motor apraxia is a deficiency in voluntary, horizontal, lateral, fast eye movements (saccades) with retention of slow pursuit movements. "Patients with AOA2 present with gait ataxia, cerebellar atrophy, sensory-motor neuropathy, ocular-motor apraxia and elevated immunoglobulins and alpha-fetoprotein levels with an age of onset (10-22years)." (PMID 21324166, 2011).
vascular tumor (14 papers, 2015 to 2023). "HCC who underwent curative resection; with high-risk factor of recurrence: 1) vascular tumor thrombus; 2) multiple nodules; 3) pre-operative AFP >200 μg/L; 4) large HCC (diameter >5 cm)." (PMID 26451613, 2015). "As for vascular tumors, hepatic hemangioendothelioma has been reported for its association with high serum AFP, though it is controversial if AFP elevation is due to the production by the tumor itself or is a hepatic response to the tumor." (PMID 26337640, 2015). "The Chi-square test showed that the patients with AFP >300 ng/ml, tumor poor differentiation (grade 3–4), micro and macro vascular tumor invasion, advanced stage (AJCC III-IV, BCLC stage B-C, and CLIP score>2) exhibited a higher risk score." (PMID 35126478, 2022). "The independent-samples t-tests suggested that the risk score distributed significantly differently in patients with different AFP levels, histology grades, vascular tumor cell type, AJCC stage, BCLC stage, and CLIP score." (PMID 35126478, 2022). "The patients with AFP >300 ng/ml, tumor poor differentiation (grade 3–4), micro and macro vascular tumor invasion, advanced stage (AJCC III-IV, BCLC stage B-C, and CLIP score >2) exhibited a higher risk score." (PMID 35126478, 2022). "In this study, we demonstrated that HBV seropositivity, AFP, incomplete tumor capsule, tumor diameter, advanced BCLC stage, and vascular tumor thrombus were independently associated with an unfavorable prognosis in HCC by the multivariate regression analysis." (PMID 35800051, 2022). "Compared to HCV-HCC patients, HBV-HCC patients were 12 years younger and had a higher proportion in males, advanced BCLC stage, vascular tumor thrombus, multiple tumor nodules, larger tumor size (≥3 cm in diameter), and higher AFP (≥20ng/mL)." (PMID 35800051, 2022). "In the training cohort, the multivariate Cox analysis indicated that age, gender, incomplete tumor capsule, vascular tumor thrombus, HBV positivity, tumor diameter, AFP, and advanced BCLC stage were independently related to OS in HCC." (PMID 35800051, 2022). "Other characteristics such as presence of dilated distal bile duct or vascular tumor embolus, the absence of thickened bile duct wall, splenomegaly and elevation of serum AFP level is also supportive of the diagnosis." (PMID 31969123, 2020).
Acute hepatitis (12 papers, 2014 to 2025). Acute hepatic injury resulting from inflammation typically accompanied by increased serum alanine transaminase activity. "Besides, AFP expression is modulated in acute hepatitis and by environmental conditions in human and in various animal models exposed to carcinogens." (PMID 25502816, 2014). "To test the diagnostic sensitivity and specificity of IL-41, we also examined the serum expression level of IL-41 in patients with acute hepatitis (including sera of patients with HBV, HCV, and autoimmune hepatitis) who were positive for AFP." (PMID 38835390, 2024).
Insulin resistance (12 papers, 2009 to 2023). Increased resistance towards insulin, that is, diminished effectiveness of insulin in reducing blood glucose levels. "hsa-miR-21-5p expression was positively correlated with serum AFP, insulin, and insulin resistance (r = 0.5, p < 0.001, r = 0.334, p = 0.01, and r = 0.303, p = 0.02, respectively)." (PMID 36834570, 2023). "Univariate Cox regression analysis reported that body mass index (P=0.013), homeostatic model assessment-insulin resistance (P=0.006), alpha-fetoprotein (P <0.001), and AGEs levels (P <0.001) were related to HCC development." (PMID 34660332, 2021). "A multivariate logistic regression analysis was used to identify potential markers, host pretreatment clinical and viral predictive factors including viral load, insulin resistance, and alpha fetoprotein (AFP) related to treatment response." (PMID 27100663, 2016). "The relationship between AFP and insulin resistance was recently examined in a retrospective analysis of 300 HCV-infected patients." (PMID 27439433, 2016). "This study draws attention to the need for further prospective studies to understand the relationship between insulin resistance, AFP, hepatic fibrosis and hepatocarcinogenesis." (PMID 27439433, 2016). "The relationship between serum AFP levels and insulin resistance seems to be unclear." (PMID 30366460, 2018). "In addition, the study will further explore the relationship between HCV, insulin resistance and AFP levels." (PMID 27439433, 2016). "However, other studies have found that levels of alpha-fetoprotein (AFP) in gestational diabetes mellitus patients were significantly higher than in normal pregnant women, suggesting that AFP may play a role in insulin resistance and metabolic changes in gestational diabetes mellitus." (PMID 37964953, 2023).
acute liver failure (11 papers, 2013 to 2024). Rapid deterioration of liver function causing encephalopathy and coagulopathy. "In recent years, alpha-fetoprotein (AFP) has turned into a prognostic marker of acute liver failure and is used as a serum marker of liver regeneration." (PMID 36569133, 2022). "As a maker of liver regeneration, alpha-fetoprotein (AFP) was found to be a parameter correlated with the outcome of acute liver failure." (PMID 32832550, 2020). "Previous studies demonstrated that AFP was a vital prognostic marker for outcomes in patients with acute liver failure." (PMID 29854714, 2018). "Previous studies demonstrated that AFP was a prognostic marker in patients with acute liver failure." (PMID 29854714, 2018). "Prior studies have shown that the serum concentrations of alpha-fetoprotein, variably elevated during liver injury, have been suggested to be of prognostic importance in acute liver failure." (PMID 23763817, 2013). "Frank’s team measured serum AFP levels on admission (median: 8.1 ng/mL) and on day 3 (median: 17.6 ng/mL) in 162 patients suffering from acute liver failure, and the result showed that AFP upregulation within day 3 may indicate a better prognosis." (PMID 36761898, 2023). "In addition, the serum AFP level reflects the function of the liver stem or progenitor cells in patients with acute liver failure." (PMID 35020772, 2022). "Previous researches have expounded that elevated AFP levels could predict a better prognosis for acute liver failure." (PMID 32832550, 2020). "Interestingly, the therapeutic efficacy of GStemHep seems to be greater than or at least equivalent to that of primary human hepatocytes (100 vs. 60% survival, but not significantly different), which confirms that immature hepatic progenitors (AFP + ALB−) can be therapeutic for acute liver failure." (PMID 38475825, 2024). "Studies have indicated that elevated AFP levels could predict a better prognosis for HBV-ACLF and acute liver failure with chronic HBV infection." (PMID 38834942, 2024).